TNF (tumor necrosis factor)
Diseases named in the same sentence as TNF in open-access papers (continued):
Sharing a sentence is not in itself a finding about the gene and the disease.
acute pancreatitis (continued). "PIN significantly suppresses the production of cyclooxygenase 2 (COX-2), which is essential for inflammation, but it has also been shown to inhibit tumor necrosis factor alpha (TNF-α), interleukin 1 beta (IL-1β), and interleukin 6 (IL-6) during acute pancreatitis." (PMID 33923276, 2021). "TNF was determined to be closely related to acute pancreatitis." (PMID 34925503, 2021). "In acute pancreatitis, melatonin has been described to play a protective role due to reduction of the gene expression and synthesis of proinflammatory cytokines such as tumor necrosis factor-α (TNFα) and proinflammatory interleukins such as interleukin (IL)-1β, IL-6, IL-8, and prostaglandins." (PMID 31007709, 2019). "In this context, our previously published data verify that pharmacologically blocking necroptosis may worsen diseases such as acute pancreatitis or vascular leakage syndrome, which is triggered by a high-dose tumor necrosis factor (TNF)." (PMID 30842945, 2019). "Compared to the untreated group, the administration of rat foetal membrane-derived mesenchymal stem cells (rat FM-MSC) into the rat penile vein after the induction of severe acute pancreatitis reduced the serum levels of proinflammatory cytokines (TNF-α and IL-6)." (PMID 29743979, 2018). "The IL-10-induced decrease in TNF-α secretion might be helpful in stabilizing the BBB, as TNF-α has been reported to increase BBB permeability in acute pancreatitis." (PMID 29497350, 2018). "First, these data indicate that acinar cells may play the active role in the development of inflammation in acute pancreatitis by releasing pro-inflammatory cytokine, TNF-α." (PMID 28665321, 2017). "TNF-α is produced in pancreatic acinar cells in experimental acute pancreatitis model." (PMID 29068376, 2017). "In the present study, an elevated level of TNF-α was obtained in rats with acute pancreatitis." (PMID 26971398, 2016). "Current use of disease modifying anti-rheumatic drugs or tumor necrosis factor blockers did not decrease the risk of acute pancreatitis." (PMID 26262880, 2015). "In the present study, RA patients taking oral glucocorticoids rather than DMARDs and TNF-blockers were found to have a reduction in the risk of acute pancreatitis." (PMID 26262880, 2015). "Furthermore, TNF-α was recently reported to play a dual role in regulating apoptosis during acute pancreatitis; a low concentration of TNF-α can induce apoptosis, whereas a high concentration causes acinar cell necrosis." (PMID 24643222, 2014). "Previous studies have revealed that inflammatory cytokines play an important role in the pathogenesis of acute pancreatitis, with the levels of TNF-α significantly higher in patients with SAP compared with those with a mild disease at the early stage of acute attack." (PMID 25371738, 2014). "Investigations into the origin of these peptides have demonstrated that intra-pancreatic cytokine levels reach concentrations several-fold higher than corresponding systemic levels, thus providing evidence that IL-1, IL-6 and TNF-α are produced within the pancreas during acute pancreatitis." (PMID 23181131, 2012). "Therefore, TNF-α can be used as a marker of the severity of acute pancreatitis." (PMID 40411704, 2025). "Additionally, considering that acute pancreatitis tends to elevate TNF-α levels 21, we investigated whether TNF-α levels displayed an analogous upregulation." (PMID 38773966, 2024). "However, in severe acute pancreatitis, there is extensive acinar cell injury, which leads to neutrophil, monocyte, and lymphocyte activation, and this results in the secretion of plenty of inflammatory mediators such as TNF-α, IL-6, and IL-10." (PMID 35296066, 2022). "Since astrocytes are known to contribute to excess levels of TNF, and hippocampal TNF/TNFR1 activity is known to promote neuropathic pain, it is plausible to suggest that hippocampal TNF/TNFR1 activity could be contributing to the induction of neuropathic pain in our model of acute pancreatitis." (PMID 34049483, 2021).
acute pancreatitis (continued). "Interestingly, intrapancreatic fat was associated with elevated circulating levels of leptin and TNF-α independent of abdominal fat distribution in patients after acute pancreatitis." (PMID 32709161, 2020). "DCQD treatment could increase the expression of anti-inflammatory cytokines (IL-4 and IL-10) and inhibit the expression of proinflammatory cytokines (TNF-α and IL-6) to ameliorate the histopathological damage of acute pancreatitis, in which higher dose DCQD seems to have the better effect." (PMID 26199633, 2015). "Interestingly, the pretreatment with diazepam (5 mg/kg i.p.)reduced significantly the inflammatory response of acute pancreatitis by ameliorating pancreatic edema, amylase and lipase serum levels, myeloperoxidase activity, pancreatic TNF-alpha, and pathological alteration compared to control group." (PMID 23956866, 2013). "The systemic inflammatory response mediated by IL-6, IL-8, TNF-α, and other cytokines, contributes to the development of HUS in Acute Pancreatitis." (PMID 40443860, 2025). "Patients with severe acute pancreatitis have been discovered to have elevated levels of TNF-α receptors, which are markers of TNF-α activity." (PMID 40150718, 2025). "Thus, it was concluded that esomeprazole could reduce serum levels of IL-β and TNF-α cytokines released from macrophages by reducing macrophage activation in rats with acute pancreatitis, showing anti-inflammatory activity and reducing the destructive effects of acute pancreatitis." (PMID 40005317, 2025). "In severe acute pancreatitis (SAP), tumor necrosis factor-alpha (TNF-α) elevates the intestinal permeability and promotes bacterial translocation from the epithelium, which further stimulates the excessive release of inflammatory cytokines and aggravates AKI." (PMID 35350960, 2022). "During the first phase of acute pancreatitis, cytokine pro-inflammation, as TNF (tumor necrosis factor) α, interleukins (IL-1, IL-2, IL-18, IL-6) and chemokine, oxygen radical oxidant are released." (PMID 34036463, 2021). "In a rat L-arginine-induced acute pancreatitis model, pretreatment with an ACE inhibitor attenuated acute pancreatitis, reduced TNF-α, and infiltrated inflammatory cells in the pancreas." (PMID 34830195, 2021). "In the severe acute pancreatitis (SAP) model, EA decreased the level of TNF-α and IL-6 in serum but increased acetylcholine (Ach) levels in serum." (PMID 35095910, 2021). "Acute pancreatitis was enhanced in PTP1B knockout mice via increased production of inflammatory cytokines, such as IL-1β, IL-6, and TNF-α." (PMID 32760098, 2020). "In another study carried out with cerulein-induced acute pancreatitis rat models, lycopene increased GSH levels and decreased the levels of MPO and inflammatory cytokines such as TNF-α and IL-1β in pancreatic tissues." (PMID 32806545, 2020). "Emodin treatment significantly reduced NF-kB DNA binding activity and the serum expression levels of TNF-α, IL-6 which led to reduced pancreatic MDA and increased SOD levels in severe acute pancreatitis rat model." (PMID 26753525, 2016). "Furthermore, treatment with TNF-blockers did not decrease risk of acute pancreatitis." (PMID 26262880, 2015). "Several signaling molecules (such as IL-1, IL-2, IL-6, PAF, substance P, TNF-α, MCP-1, and NF-κB) have been shown to play important roles in the progression of experimental acute pancreatitis." (PMID 25147563, 2014). "Previously, a beneficial effect of PTX treatment was demonstrated in rats submitted to acute pancreatitis and showed that PTX very effectively decreased TNF-alpha and IL-6 production under this condition." (PMID 24991532, 2014).
acute pancreatitis (continued). "In a rat model of acute pancreatitis, the infusion of anti-PAP1 antibodies worsened the pancreatic inflammatory response and PAP1 treatment prevented tumor necrosis factor (TNF)-α-induced Nuclear Factor kappa B (NF–κB) activation in macrophages." (PMID 22195011, 2011). "Although we measured only IL-6 and TNF, other inflammatory mediators known to play a critical role in acute pancreatitis and MODS include TNFa, IL-1b, IL-6, IL-8, platelet-activating factor, and IL-10." (PMID 20015376, 2009). "IL-8 in early phase of acute pancreatitis is superior marker compared to CRP and TNF-α for distinguishing patients with severe disease." (PMID 20130823, 2009). "In fact, there is some evidence that DENV infection ultimately elicits production of cytokines such as tumor necrosis factor alpha, transforming growth factor beta, and interleukin 10, otherwise observed in studies on non-DENV-associated acute pancreatitis." (PMID 41441569, 2025). "The recent documentation of TNF-α's proinflammatory role in animal models of ALI/ARDS induced by LPS and severe acute pancreatitis suggests that targeting TNF-α could be an attractive therapeutic approach for ARDS." (PMID 38218783, 2024). "Clinical evidence showed that UTI had a significant effect on inflammatory biomarkers such as C-reactive protein (CRP), interleukin-6 (IL-6), and tumor necrosis factor-alpha (TNF-α), as well as reduced and prevented MODS and lowered mortality in acute pancreatitis." (PMID 35634310, 2022). "Studies suggested that calycosin could diminish the levels of TNF-α, IL-6, and IL1B in mice with acute pancreatitis." (PMID 35227280, 2022). "It is reported that the spleen is the main source of TNF production, and rats with splenectomy reduced the levels of inflammatory cytokines and leukocyte infiltration and developed acute pancreatitis more slowly than rats without splenectomy." (PMID 34262881, 2021). "Importantly, sEH inhibition reduces the circulating levels and the expression of pancreatic mRNA of inflammatory cytokines, including tumor necrosis factor (TNF)-α, interleukin (IL)-1β, and IL-6 in experimental acute pancreatitis in mice." (PMID 34607951, 2021). "The results of this study suggest that eugenol attenuates the intensity of the histopathological changes and the expression of TNF-α and MPO in the renal parenchyma, while lowering the values of serum urea and creatinine when administered in a rat acute pancreatitis experimental model." (PMID 26884642, 2016). "Nevertheless, our study did not demonstrate a role of TNF-α as a predictive marker of the severity of acute pancreatitis." (PMID 20130823, 2009). "Furthermore, in an acute pancreatitis mouse model, 1,8‐cineole administration resulted in lower cytokine levels of TNF‐α, IL‐1β, and IL‐6, reflecting the results found with thalidomide, a TNF‐α inhibitor." (PMID 40719271, 2025). "The most common marker of acute pancreatitis is the transformation of quiescent PSCs (positive to glial fibrillary acidic protein (GFAP)) into activated PSCs (positive to α-smooth muscle actin (α-SMA)), and tumor necrosis factor alpha (TNFα) seems to be mainly responsible for its activation." (PMID 35277074, 2022). "Since that acute pancreatitis is an inflammatory disorder of the pancreas, we have also detected that VB 12 reduced the level of MPO in the AP model in vivo and reduced the level of inflammatory factors IL-1β and TNF-α in the supernatant of acinar cell culture in vitro." (PMID 34925701, 2021). "Orlistat was shown to decrease IL-6 and TNFα in diabetic patients, and to reduce systemic inflammation and pancreatitis-induced death in obese (ob/ob) mice as measured by a lower mortality incidence and decreased serum levels of TNFα, MCP-1 and IL-6 in an acute pancreatitis mouse model." (PMID 33440724, 2021).
acute pancreatitis (continued). "Platelet-activating factor antagonists such as lexipafant, antioxidants, corticosteroids, nitroglycerin, anti-interleukin-10 (anti-IL-10) antibodies, and anti-tumor necrosis factor-alpha (anti-TNF-α) antibodies have been shown to be of no value in the treatment of acute pancreatitis." (PMID 26918139, 2015). "In rats with ablation of sensory nerves before induction of acute pancreatitis, pretreatment with ghrelin was without any effect on morphological signs of pancreatic damage, pancreatic weight, plasma level of pancreatic digestive enzyme, lipase or plasma concentration of TNF-α and IL-4." (PMID 28665321, 2017). "Recent studies have suggested that the serum levels of interleukins and TNF-α may be used to identify patients who are prone to develop local or systemic complications and were compared with CRP which has been employed in the prediction of severity of acute pancreatitis." (PMID 20130823, 2009). "Other studies over the last few years have suggested that serum levels of interleukins and TNF-α may be used to identify patients who are prone to develop local or systemic complications and were compared with CRP which has been employed in the prediction of severity of acute pancreatitis." (PMID 20130823, 2009).
myocarditis (160 papers, 2004 to 2026). Myocarditis is a condition that is characterized by inflammation of the heart muscle (myocardium). "NLRP3 activation leads to the release of interleukin-1β (IL-1β), tumor necrosis factor-alpha (TNF-α), and interleukin-6 (IL-6), cytokines that are directly implicated in the pathogenesis of myocarditis and other cardiovascular inflammatory disorders." (PMID 40870916, 2025). "TNF-α is another active inflammatory cytokine that has been found elevated in mice cardiac tissue with myocarditis and has been implicated in autoimmune myocarditis." (PMID 36851240, 2023). "TNF-α inhibitors have also been studied and used in the treatment of myocarditis and IPF, strengthening the association between TNF-α and fibrosis." (PMID 36851240, 2023). "The other possibility involves the virus triggering immune response in the form of cytokine storm releasing IL-6, IL-10, and TNF-alpha, causing myocarditis." (PMID 36902636, 2023). "Established models and clinical data have demonstrated a causal role for TNF-α in virus-induced myocarditis." (PMID 35602592, 2022). "Alternatively, virus can trigger inflammatory response in the form of SIRS, lymphopenia, macrophage activation and cytokine storm releasing IL-6, IL-10 and TNF-α which can cause myocarditis." (PMID 33615872, 2021). "An initial study showed that the cardiac-restricted overexpression of TNF-α caused lethal myocarditis with diffuse lymphohistiocytic infiltrates and interstitial edema that led to cardiac death at the age of 7–11 days." (PMID 33053859, 2020). "Other Th1-related pro-inflammatory cytokines like IL-1β, TNF-α, and IL-12 play pathogenic roles in myocarditis as well." (PMID 32269577, 2020). "In patients with enteroviral-induced myocarditis, TNF-α levels are often increased and are associated with increased myocardial necrosis and cellular infiltration in the myocardium." (PMID 19587788, 2009). "TNF-α and IL-1β levels are significantly increased in the heart during the innate (6 hours after infection) and adaptive (during acute myocarditis) immune response in susceptible strains of mice (i.e. BALB/c) that develop chronic myocarditis and DCM." (PMID 23675015, 2007). "In addition, the TNF/TNFR1 signaling cascade has previously been linked to the development of CD8-enriched myocarditis and the underlying pathophysiology during T. cruzi infection." (PMID 38390336, 2024). "There is growing evidence that suggests that males have a higher risk of outcomes in the case of myocarditis, despite the fact that they are able to suppress the production of pro-inflammatory cytokines (IL-1β, IL-6 and TNF-α) and increasing the production of anti-inflammatory cytokines." (PMID 37112659, 2023). "It has been indicated that inflammatory reactions are implicated in myocarditis and that a wide range of inflammatory factors, including TNF-α and IL-6, might be toxic to myocardial cells." (PMID 32515469, 2020). "TNF-α has biological activities, such as inducing anti-infection effectsand promoting cell proliferation and differentiation, which can be directly involved in immune processes caused by myocarditis and other diseases." (PMID 33817135, 2019). "Although IL-17A alone reproduces key aspects of autoimmune-driven fibrosis, future organoid models will incorporate a multifactorial cytokine environment (e.g., TNF-α + TGF-β + IL-17A) to better mimic viral or mixed etiology myocarditis." (PMID 41356193, 2026). "Patients with acute myocarditis also have increased serum levels of pro-inflammatory cytokines, including interleukin (IL)−1ɑ, IL-1β, and tumor necrosis factor (TNF)-ɑ." (PMID 40146392, 2025). "It has been reported that transgenic mice overexpressing IFN-γ in plasma develop a TNF-α dependent myocarditis and cardiomyopathy." (PMID 40297326, 2025).